PGR (progesterone receptor)
Diseases named in the same sentence as PGR in open-access papers (continued):
Sharing a sentence is not in itself a finding about the gene and the disease.
triple-negative breast carcinoma (continued). "Although defined by the absence of estrogen receptor, progesterone receptor, and ERBB2 expression, genomic analyses have revealed intrinsic triple-negative breast cancer subtypes, including basal-like (BL1 and BL2), mesenchymal, luminal androgen receptor, and immunomodulatory subtypes." (PMID 40373794, 2025). "In particular, triple-negative breast cancer (TNBC), which is estrogen receptor (ER)-negative, progesterone receptor (PgR)-negative and human epidermal growth factor receptor 2 (HER2)-negative, has been reported to have higher rates of recurrence and mortality compared to those in other types." (PMID 40862810, 2025). "Triple-negative breast cancer (TNBC), characterized by the absence of estrogen receptor (ER), progesterone receptor (PR), and human epidermal growth factor receptor type 2 (HER2) expression, represents a therapeutic challenge due to its aggressive nature and limited treatment options." (PMID 40497992, 2025). "Triple-negative breast cancer (TNBC) is defined by the lack of expression of estrogen receptor (ER), progesterone receptor (PR), and human epidermal growth factor receptor 2 (HER2)—key molecular markers that are routinely utilized for breast cancer classification and therapeutic decision-making." (PMID 40943224, 2025). "Triple-negative breast cancer (TNBC) is a highly aggressive and heterogeneous malignancy characterized by the absence of estrogen receptor (ER)and progesterone receptor (PR), and the lack of amplification/overexpression of human epidermal growth factor receptor 2 (HER2)." (PMID 41198671, 2025). "Breast tumours that express the ER and/or progesterone receptor (PR) are quoted to be “hormone receptor-positive” BCs, whereas those that do not express the ER, PR, or HER2 are referred to as “triple-negative breast cancers” (TNBC) which is well-thought-out to be the most antagonistic." (PMID 39574432, 2024). "Triple-negative breast cancer (TNBC), which is clinically defined by the absence of expression of human epidermal growth factor receptor 2 (HER2), progesterone receptor (PR), and estrogen receptor (ER), contributes to approximately 15–20% of all breast cancer cases." (PMID 39795893, 2024). "Triple-negative breast cancer (TNBC) has been evolved as most aggressive type of BC due to its lack of estrogen receptor (ER), progesterone receptor (PR), and human epidermal growth factor receptor 2 (HER-2), resulting in un-responsiveness towards endocrine therapy or anti-HER2 treatment." (PMID 39103624, 2024). "The normal breast-like subtype is also known as triple-negative breast cancer (TNBC), because it lacks expression of HER2, ER, and PgR; however, unlike the basal-like subtype, which similarly lacks these three hormone receptors, TNBC is also negative for keratin 5 (CK5) and EGFR expression." (PMID 37432459, 2023). "And approximately 10–20% breast cancers which lack of estrogen receptor, progesterone receptor (PR) and human epidermal growth factor receptor 2 (HER2) were classified into triple negative breast cancer (TNBC) and always posed therapeutic challenges for TNBC patients." (PMID 38040691, 2023). "On the other hand, long-term prognosis and therapeutic options are much poorer in triple-negative breast cancers (TNBC), which by definition do not express ERα and progesterone receptor (PR), and do not overexpress the receptor tyrosine-protein kinase erbB-2 (HER2)." (PMID 36902090, 2023). "Triple-negative breast cancer (TNBC) refers to breast cancer with negative estrogen receptor (ER), progesterone receptor (PR) and proto-oncogene Her-2, accounting for 15–20% of all pathological types of breast cancer, with a special biological behavior and clinical pathological characteristics." (PMID 37173608, 2023).
triple-negative breast carcinoma (continued). "Breast cancers can be classified into distinct subtypes: estrogen receptor positive (ER+), human epidermal growth factor receptor 2 (HER2) amplified, and triple-negative breast cancer (TNBC) defined by the absence of ER and progesterone receptor (PR) expression and HER2 amplification." (PMID 37046596, 2023). "Although the majority of BLBCs overlap with triple-negative breast cancer (TNBC) (defined as lacking the expression of the estrogen receptor (ER), progesterone receptor (PR), and human epidermal growth factor receptor 2 (HER2)), about 20% of BLBCs are known to express ER or HER2." (PMID 36674955, 2023). "Triple-negative breast cancer (TNBC) is a subtype of breast cancer characterized by the negative expression of estrogen receptor (ER), progesterone receptor (PR) and human epidermal growth factor receptor-2 (HER-2), and it accounts for 15-20% of all breast cancers." (PMID 37731509, 2023). "Triple-negative breast cancer (TNBC) is characterized by a lack of expression of estrogen receptor (ER), progesterone receptor (PR), and human epidermal growth factor receptor 2 (HER2/neu) and exhibits high invasiveness, poor prognosis, and a high recurrence rate." (PMID 37762493, 2023). "Triple-negative breast cancer (TNBC), which is distinguished by the absent expression of human epidermal growth factor receptor 2 (Her2) and estrogen receptor/progesterone receptor (ER/PR), is the most invasive subtype with the highest mortality rate accounting for approximately 15% of all BRCA." (PMID 36052076, 2022). "MBC is characterized by strong invasiveness, poor prognosis, and is often negative in estrogen receptor (ER), progesterone receptor (PR), and human epidermal growth factor receptor 2 (HER2) tests; its prognosis is worse than that of triple-negative breast cancer, and the survival rate is lower." (PMID 36092916, 2022). "Triple-negative breast cancer (TNBC), which is characterized by the lack of expression of estrogen receptor (ER), progesterone receptor (PR), and expression/amplification of human epidermal growth factor receptor 2 (HER2), is the most aggressive and difficult-to-treat subtype of breast cancer." (PMID 35174077, 2022). "Triple negative breast cancers (TNBC) are a heterogenous group of diseases, defined by the absence of detectable estrogen and progesterone receptors (ESR1, PGR), non-amplified/normally expressed Her2 receptor (ERBB2), and characterized by aggressive clinical behaviour and poor prognosis." (PMID 35927228, 2022). "Triple-negative breast cancer (TNBC), a phenotypic subtype characterized by a lack of oestrogen receptor (ER), progesterone receptor (PR), and human epidermal growth factor receptor 2 (HER2) expression, is an aggressive form of breast cancer associated with a poor prognosis." (PMID 35574419, 2022). "However, triple-negative breast cancer (TNBC) is characterized by the lack of expression of estrogen receptor (ER), progesterone receptor (PR) and HER2, rendering targeted therapeutic options limited." (PMID 35158750, 2022). "Triple negative breast cancer (TNBC), defined by lack of expression of the ER, progesterone receptor (PgR), and HER2, accounts for 10–20% of invasive breast cancer, and carries a relatively worse prognosis, with higher rates of metastasis and recurrence, and higher mortality." (PMID 35729608, 2022). "Triple-negative breast cancer (TNBC) is a subtype of breast cancer that accounts for 10–15% of breast cancers, characterized by a lack of estrogen receptor (ER), progesterone receptor (PR), and an expression of low levels of human epidermal growth factor 2 (HER2)." (PMID 36555393, 2022). "Of those diagnosed with breast cancer, 15–20% are classified as triple-negative breast cancer (TNBC), which is identified by the absence of an estrogen receptor (ER) and a progesterone receptor (PR) and does not make too much of epidermal growth factor receptor type 2 (Erbb2/HER2)." (PMID 34680349, 2021).
triple-negative breast carcinoma (continued). "Triple receptor negative breast cancer (TNBC) is a molecular subtype characterized by the lack of estrogen receptor (ER), progesterone receptor (PR), and receptor for human epidermal growth factor-2 (HER2), making it unsuitable for endocrine or targeted antibody therapy." (PMID 33445642, 2021). "Triple-negative breast cancer (TNBC) is an aggressive breast cancer subtype, characterized by the absence of estrogen receptor (ER) and progesterone receptor (PR) expression, as well as lack of gene amplification and/or protein overexpression of the human epidermal growth factor receptor 2 (HER2)." (PMID 34638394, 2021). "A tumor lacking ER, PgR, and HER2 is called triple-negative breast cancer (TNBC)." (PMID 34070471, 2021). "Triple-negative breast cancer (TNBC), lacking the expression of estrogen receptor (ER), progesterone receptor (PR), and human epidermal growth factor receptor 2 (HER-2), accounts for about 10–15% and is the most aggressive molecular subtype of all breast tumors." (PMID 34805180, 2021). "Among the breast cancer molecular subtypes, triple negative breast cancer (TNBC), accounting for 15–20% of all breast cancers, is defined by the absence of estrogen receptor (ER), progesterone receptor (PR), and human epidermal growth factor receptor-2 (Her-2) expression." (PMID 33324565, 2020). "Triple-negative breast cancer (TNBC) is used to describe a subset of breast cancers and is defined as the lack of expression of estrogen receptor (ER) and progesterone receptor (PR) and the absence of human epidermal growth factor receptor 2 (HER2) overexpression and/or gene amplification." (PMID 33046986, 2020). "Triple-negative breast cancer (TNBC) is clinically defined by the lack of expression of estrogen receptor (ER), progesterone receptor (PR), and lack of overexpression/amplification of human epidermal growth factor receptor-2 (HER2) proteins or HER2 gene copies." (PMID 32256581, 2020). "The triple-negative breast cancer (TNBC), which accounts for 10–20% of all breast malignancies, is characterized by the absence of the estrogen receptor (ER) and the progesterone receptor (PR) without the amplification of the human epidermal growth factor receptor 2 (HER2)." (PMID 32778144, 2020). "Patients with the triple negative breast cancer (TNBC) subtype, characterized by the absence of ER, progesterone receptor (PR), and human epidermal growth factor receptor-2/neu receptors (HER2/neu) have a poor prognosis also due to the few clinical treatments available." (PMID 31998443, 2020). "Triple-negative breast cancer (TNBC) is a notoriously aggressive, heterogeneous disease defined as lacking expression of oestrogen receptor (ER) and/or progesterone receptor (PR) as well as amplification of human epidermal growth factor receptor 2 (HER2), respectively." (PMID 31262335, 2019). "However, treatment of triple-negative breast cancers (TNBC) that do not express high levels of HER2/ERBB2, ER, or progesterone receptor (PR) remains a major therapeutic challenge." (PMID 31448050, 2019). "Triple-negative breast cancer (TNBC) has a distinct aggressive molecular subtype, characterized by lack of progesterone receptor (PR), estrogen receptor (ER), and human epidermal growth factor receptor-2 (HER-2) expression resulting in poorer outcomes than other subtypes." (PMID 30518369, 2018). "Furthermore, most patients had ER (71%) and PgR (58.5%) positive status, high MIB1 (57.9%) and HER2/neu negative (50.6%); 10.4% were triple negative breast cancers." (PMID 29716631, 2018). "Interestingly, the C19MChigh group harbored significantly downregulated expression of PGR, ESR1 and ERBB2 mRNAs compared to C19MClow group, the candidate “negative markers” of triple negative breast cancers." (PMID 30335837, 2018).
triple-negative breast carcinoma (continued). "There are different types of breast cancer based on pathological examination: estrogen receptor (ER)+, human epidermal growth factor receptor 2 (HER2)+ and triple negative breast cancer (TNBC) (the absence of ER, HER2, and progesterone receptor (PR) expression)." (PMID 30287735, 2018). "Triple-negative breast cancer (TNBC) is a breast cancer phenotype characterized by an immunohistochemical absence of estrogen receptor (ER) and progesterone receptor (PR), as well as absence of amplification of the human epidermal growth factor receptor 2 (HER2) gene." (PMID 30566471, 2018). "Separately, breast cancers with a combined negative expression of estrogen receptor (ER), progesterone receptor (PR), and human epidermal growth factor receptor 2 (HER-2), which has therapeutic implications, are classified as triple-negative breast cancer (TNBC)." (PMID 29682102, 2018). "Triple negative breast cancer (TNBC) is a heterogeneous group of clinically aggressive breast cancers, designated as pathologically negative for estrogen receptor (ER−), progesterone receptor (PR−), and human epidermal growth factor receptor 2 amplification (HER2−)." (PMID 30564555, 2018). "Unlike hormone-receptor-positive tumours that express the oestrogen receptor (ER) and progesterone receptor (PR), or HER-2-positive neoplasms that express the erb-b2 transmembrane receptor, triple-negative breast cancers (TNBCs) are negative for all three receptors." (PMID 29720474, 2018). "Triple-negative breast cancer (TNBC) is not a simple, homogeneous breast cancer subtype; it collectively describes cancers that do not express the well-known target receptors estrogen receptor (ER), progesterone receptor (PR), and HER2." (PMID 29050296, 2017). "The triple-negative breast cancer subtype (TNBC; defined by molecular markers) and the basal subtype (defined by histology) overlap extensively; both classes are predominately negative for estrogen receptor (ER), progesterone receptor (PR), and Her23." (PMID 28165048, 2017). "Triple-negative breast cancer (TNBC) lacking estrogen receptor (ER), progesterone receptor (PR), and human epidermal growth factor receptor 2 (HER2) expression, is a highly invasive and metastatic form of breast cancer with a generally poorer prognosis than that of other breast cancer subtypes." (PMID 27484639, 2016). "Among these, the basal-like subtype exhibits characteristics similar to myoepithelial/basal cells, with many cases consistent with triple-negative breast cancer (TNBC), in that they are immunohistochemically ER negative, progesterone receptor (PgR) negative and HER2 negative." (PMID 26757422, 2016). "Triple-negative breast cancer (TNBC), closely related to basal-like breast cancer (BLBC), is characterized by an absence of estrogen receptor (ER) and progesterone receptor (PR) expression and a lack of human epidermal growth factor receptor 2 (HER2) overexpression/amplification." (PMID 25848952, 2015). "Triple-negative breast cancer (TNBC) refers to a type of breast cancer with negative estrogen receptor (ER), negative progesterone receptor (PR) and negative human epidermal growth factor receptor 2 (Her2) expression, accompanied by characteristic pathological features and molecular expression." (PMID 25435949, 2015). "Triple-negative breast cancer (TNBC), i.e., breast cancer characterized by no immunohistochemical expression of the estrogen receptor (ER) or progesterone receptor (PR) and the absence of human epidermal growth factor receptor 2 (HER-2) overexpression, accounts for 15–20% of breast cancer cases." (PMID 26083025, 2015). "Triple negative breast cancer (TNBC), defined by the lack of expression of the estrogen receptor, progesterone receptor and human epidermal receptor 2 (HER2), is characterized by an aggressive clinical course, an earlier age of diagnosis, and lacks efficient treatment." (PMID 25961742, 2015).
triple-negative breast carcinoma (continued). "Interrogation of expression databases showed that RIP2 expression is significantly over-expressed in triple-negative breast cancers (TNBC: estrogen-receptor (ER) negative, progesterone-receptor (PR) negative, Her2/neu- (Her2) negative), compared to other clinical subtypes." (PMID 24642040, 2014). "Triple negative breast cancer (TNBC) represents an important clinical subtype, characterised by an absence of estrogen receptor (ER), progesterone receptor (PR) and human epidermal growth factor receptor 2 (HER2) and which therefore lack common targets used for anti-hormone therapies." (PMID 24725360, 2014). "Triple-negative breast cancer (TNBC), which comprises 15–20% of all breast cancer, is considered the most aggressive type of breast cancer due to the lack of estrogen receptor (ER), progesterone receptor (PR), and human epidermal growth factor receptor 2 (HER2) expressions for treatments." (PMID 38794146, 2024). "Triple-negative breast cancers (TNBC) are characterized by the absence of estrogen, progesterone, and ERBB2 receptors, and are specifically identified as estrogen receptor (ER)-negative, progesterone receptor (PR)-negative, and human epidermal growth factor receptor 2 (HER2)." (PMID 40860264, 2024). "Triple-negative breast cancer (TNBC) is aggressive and presents unique clinical challenges and limited treatment options due to the absence of the targetable estrogen receptor (ER), progesterone receptor (PR), and the human epidermal growth factor receptor 2 (HER2)." (PMID 38791938, 2024). "The ‘triple-negative breast cancer (TNBC)’, seen among 10–15% of patients, is the most challenging type of breast cancer and is characterised by a lack of expression of the estrogen receptor (ER), Progesterone receptor (PR) and human epidermal growth factor receptor-2 (HER2)." (PMID 37629702, 2023). "Triple-negative breast cancer (TNBC) is a breast cancer subtype that accounts for approximately 15% of all breast cancers and is characterized by the absence of the expression of the estrogen receptor (ER), progesterone receptor (PR), and human epidermal growth factor 2 receptor (HER2)." (PMID 37530973, 2023). "Importantly, triple negative breast cancer (TNBC), defined by lack of estrogen receptor (ER), progesterone receptor (PR), and human epidermal growth factor receptor-2 (HER2) expression, remains associated with shorter disease-free interval and higher mortality rate." (PMID 29902993, 2018). "However, triple negative-breast cancer (TNBC), which is characterized by the lack of an estrogen receptor (ER), progesterone receptor (PR), and Her-2 overexpression, could not benefit from both endocrine therapy and Her-2 targeted therapy." (PMID 26910840, 2016). "Of the 15 patients, 10 had triple-negative breast cancer, 2 had estrogen receptor-positive disease, HER2-positive disease, 2 had estrogen receptor-positive disease, HER2-negative disease and 1 had estrogen receptor-negative disease, progesterone receptor-positive disease, and HER2-negative disease." (PMID 28721364, 2015). "Triple-negative breast cancer (TNBC) is a therapeutically relevant definition of a subgroup of breast cancers (BCs) characterized by the absence of staining for the estrogen receptor (ER), the progesterone receptor (PR), and human epidermal factor receptor 2 (HER2)." (PMID 25393310, 2014).